CYB561D2 (cytochrome b561 family member D2)
Description:
Transmembrane reductase that may use ascorbate as an electron donor in the cytoplasm and transfer electrons across endoplasmic reticulum membranes to reduce monodehydro-L-ascorbate radical and iron cations Fe(3+) in the lumen of that compartment.
Synonyms: 101F6; TSP10; TSCytb; XXcos-LUCA11.4
Tractability: Antibody: UniProt predicts a signal peptide or a membrane-spanning region.
Gene: Protein-coding gene on chromosome 3 (50,350,839 to 50,358,460, forward strand). Ensembl gene ENSG00000114395.
Subcellular location: Endoplasmic reticulum membrane; Cytoplasmic vesicle membrane
Gene Ontology:
Molecular function: heme binding; protein binding; transmembrane monodehydroascorbate reductase activity; transmembrane ascorbate ferrireductase activity; oxidoreductase activity
Biological process: ascorbate homeostasis; transmembrane transport
Cellular component: cytoplasmic vesicle membrane; endoplasmic reticulum; endoplasmic reticulum membrane; vesicle
Genetic constraint (gnomAD): Loss-of-function variants: 16 observed, 21.4 expected, observed/expected ratio (o/e) 0.75, 90% interval 0.5 to 1.13. The upper end of that interval is the gene's LOEUF score, 1.13, which puts it in group 4 of 6, group 1 being the genes least tolerant of losing a copy. Missense variants: 247 observed, 282.08 expected, observed/expected ratio (o/e) 0.88, 90% interval 0.79 to 0.97. Synonymous variants: 135 observed, 132.98 expected, observed/expected ratio (o/e) 1.02, 90% interval 0.88 to 1.17.
Homologues: Orthologues: chimpanzee CYB561D2 (99% identical), macaque CYB561D2 (98% identical), rat Cyb561d2 (96% identical), mouse Cyb561d2 (95% identical), pig CYB561D2 (95% identical), rabbit CYB561D2 (95% identical), dog CYB561D2 (95% identical), guinea pig CYB561D2 (94% identical), tropical clawed frog cyb561d2 (64% identical), zebrafish cyb561d2 (53% identical), Drosophila melanogaster CG10165 (26% identical), Drosophila melanogaster CG13077 (21% identical), and 1 more. Paralogues in human: CYB561D1 (50% identical).
Diseases named in the same sentence as CYB561D2 in open-access papers:
CYB561D2 is named in the same sentence as 7 diseases in open-access papers, as found by Europe PMC text mining. Sharing a sentence is not in itself a finding about the gene and the disease. The quoted sentences say what the papers report.
glioma (5 papers, 2017 to 2024). A benign or malignant brain and spinal cord tumor that arises from glial cells (astrocytes, oligodendrocytes, ependymal cells). "Taken together, it suggests that CYB561D2 expression was robustly increased in gliomas and was associated with high histological grade and short survival." (PMID 34372858, 2021). "CYB561D2 up-regulation was associated with high grading of gliomas and short survival in patients." (PMID 34372858, 2021). "CYB561D2 protein level was further investigated by immunohistochemistry in the sections from the same glioma and control samples." (PMID 34372858, 2021). "It reveals that CYB561D2 is an important mediator of the crosstalk between ROS and immune checkpoints in gliomas." (PMID 34372858, 2021). "CYB561D2 up-regulation induces immunosuppression and aggression via activating STAT3 in gliomas and CYB561D2 mediates ROS-tumor immunity crosstalk." (PMID 34372858, 2021). "To avoid potential bias from small sample size, we cross-validated CYB561D2 up-regulation in two large independent glioma datasets and both show robust up-regulation of CYB561D2 in gliomas." (PMID 34372858, 2021). "Taken together, these results suggest that CYB561D2 regulates the expression of immunosuppressive genes in glioma cells." (PMID 34372858, 2021). "These robust and reproducible results strongly support that CYB561D2 plays an oncogenic role in gliomas." (PMID 34372858, 2021). "Here, we provide a detailed characterization of CYB561D2 in gliomas and our results suggest that CYB561D2 up-regulation induces immunosuppression and aggression via activating STAT3 in gliomas." (PMID 34372858, 2021). "Western blot and its quantification show that CYB561D2 protein levels were increased in gliomas compared to control tissues, and were further increased in high-grade gliomas." (PMID 34372858, 2021). "Taken together, these results further confirm that CYB561D2 up-regulation activates STAT3 in gliomas and CYB561D2-activated STAT3 might modulate target gene expression to regulate tumor behaviors." (PMID 34372858, 2021). "Given the strong association of CYB561D2 with survival of patients and the important roles of CYB561D2 in the homeostasis of oxidation–reduction reaction, we hypothesize that CYB561D2 is potentially involved in the pathogenesis of gliomas." (PMID 34372858, 2021). "Both datasets show a robust up-regulation of CYB561D2 in gliomas compared to control tissues." (PMID 34372858, 2021). "CYB561D2 expression was enhanced in gliomas compared to control tissues." (PMID 34372858, 2021). "Thus, our results support that CYB561D2 plays an oncogenic role through activating STAT3 in gliomas." (PMID 34372858, 2021). "CYB561D2, an antioxidant protein, is part of 5-gene prognosis signature in gliomas and its involvement in gliomas is unknown." (PMID 34372858, 2021). "Similarly, qPCR result shows that CYB561D2 mRNA levels were also increased in gliomas compared to control tissues, and were further increased in high-grade gliomas." (PMID 34372858, 2021). "As an antioxidant protein, CYB561D2 expression was up-regulated in gliomas by H2O2." (PMID 34372858, 2021). "Here, we aim to provide a detailed characterization of CYB561D2 in gliomas." (PMID 34372858, 2021). "Taken together, these results support that CYB561D2 up-regulation in gliomas could result in immunosuppression of T cells via STAT3." (PMID 34372858, 2021). "Kaplan–Meier method was used to explore whether CYB561D2 expression could affect survival of patients in REMBRANDT glioma and TCGA GBM datasets." (PMID 34372858, 2021). "Thus, CYB561D2 might regulate immunosuppressive gene expression to affect the efficacy of immunotherapy in gliomas." (PMID 34372858, 2021). "In an experiment conducted on glioma cells, it was observed that H2O2 induced the expression of CYB561D2, an antioxidant protein." (PMID 37469162, 2024).
glioma (continued). "To cross-validate CYB561D2 up-regulation, we explored expression data from REMBRANDT glioma (total n = 524) and TCGA GBM (total n = 454) datasets." (PMID 34372858, 2021). "Therefore, CYB561D2 may play an important role in the aggression of gliomas." (PMID 34372858, 2021). "As CYB561D2 is essential for the homeostasis of ascorbate, we also measured intra-cellular ascorbate levels in H2O2 treated glioma cell lines." (PMID 34372858, 2021). "Thus, targeting CYB561D2 might be a plausible strategy to treat gliomas." (PMID 34372858, 2021). "In summary, we show that CYB561D2 up-regulation induces immunosuppression and aggression via activating STAT3 in gliomas." (PMID 34372858, 2021). "Taken together, these results suggest that H2O2 treatment could induce CYB561D2 expression and activate STAT3 in glioma cells." (PMID 34372858, 2021). "A 20-gene signature was identified, which was associated with radiotherapy.Furthermore, a novel 5-gene signature (HOXC10, LOC101928747, CYB561D2, RPL36A and RPS4XP2) as an independent predictor of glioma patients’ prognosis was further derived from the 20-gene signature." (PMID 29179492, 2017).
lung carcinoma (3 papers, 2007 to 2023). "A previous study reported that Cyb561d2 can inhibit the genesis and development of lung cancer by its inhibitory effects on cell growth." (PMID 36829869, 2023). "We have noticed that previous studies identified CYB561D2 as a tumor suppressor in lung cancer because of its genetic deletion in some cases and its inhibitory effects on tumor cell growth in certain cell lines." (PMID 34372858, 2021). "But it’s an open question that whether and how is CYB561D2 involved in cancers beyond lung cancer." (PMID 34372858, 2021).
brain tumor (1 paper, 2022). "LncRNA CYB561D2 has been indicated to activate STAT3 and lead to the immunosuppression in brain tumor." (PMID 36289463, 2022).
epilepsy (1 paper, 2022). A brain disorder characterized by episodes of abnormally increased neuronal discharge resulting in transient episodes of sensory or motor neurological dysfunction, or psychic dysfunction. "The chromosome 3 region spans 159 genes, including neuronal development genes SEMA3F and SEMA3B, and epilepsy-associated genes NPRL2, CACNA2D2, and CYB561D2." (PMID 35190550, 2022).
psoriasis (1 paper, 2023). An autoimmune condition characterized by red, well-delineated plaques with silvery scales that are usually on the extensor surfaces and scalp. "A novel finding in our study was the potential function of Cyb561d2 in psoriasis." (PMID 36829869, 2023). "Thus, we speculated that Cyb561d2 might regulate ferrous iron generation to affect lipid peroxidation in ferroptosis activation in psoriasis." (PMID 36829869, 2023). "However, there was no report on the role of Cyb561d2 in psoriasis or ferroptosis." (PMID 36829869, 2023).
cancer (4 papers, 2020 to 2025). A tumor composed of atypical neoplastic, often pleomorphic cells that invade other tissues. "As increased intra-cellular ROS level is a common feature shared by many types of cancers and CYB561D2 is involved in oxidation–reduction reaction, we investigated whether CYB561D2 up-regulation is resulted from ROS over-accumulation." (PMID 34372858, 2021).
tumor (4 papers, 2010 to 2021). "As CYB561D2 expression is correlated with poor prognosis in patients, manipulation of CYB561D2 expression may modulate tumor behaviors." (PMID 34372858, 2021). "It reveals that CYB561D2 mediates the crosstalk between ROS and tumor immunity." (PMID 34372858, 2021). "It reveals a novel role of CYB561D2 in mediating the crosstalk between ROS and tumor immunity." (PMID 34372858, 2021). "The candidate region on 3p21.3 harbors various tumor suppressor genes (HYAL2, FUS1, RASSF1, BLU, NPR2L, CYB561D2, PL6 and CACNA2D2)." (PMID 20678252, 2010).